FGF9 (fibroblast growth factor 9)
Diseases named in the same sentence as FGF9 in open-access papers (continued):
Sharing a sentence is not in itself a finding about the gene and the disease.
cancer (continued). "Although miR‐372‐3p has been found to regulate cancer development by suppressing various genes in various tumors 32, 33, 34, it was worth mentioning that the FGF9 was chosen as the candidate target gene using bioinformatics analysis." (PMID 28440022, 2017). "Because FGF9 is a potent mitogen and survival factor, induction of its expression provides a key factor for cancer cells to survive and proliferate under unfavorable conditions like hypoxia." (PMID 24334956, 2014). "The levels of FGF9 protein were significantly increased in cancer cells compared with normal counterparts." (PMID 24334956, 2014). "Furthermore, in the cocultures of CAFs and DU 145 cancer cells, the blockage of TNF-α by the neutralizing antibodies against TNF-α, TNFR1, and TNFR2 effectively eliminated the increase in Fgf9 secretion by CAFs caused by KLF5KR knockin." (PMID 38781024, 2024). "deAc-KLF5 upregulates TNF-α in cancer cells to increase FGF9 release by CAFs." (PMID 38781024, 2024). "Furthermore, a recent publication suggested a role for FGF9 in resistance to the commonly used anti-cancer agent gemcitabine." (PMID 35193394, 2022). "Indeed, FGF9 has been found to be highly expressed in HCC, and significantly associated with the proliferation of cancer cells." (PMID 34868990, 2021). "In cancers, FGF9 overexpression accelerates lung adenocarcinoma." (PMID 33234721, 2020). "Furthermore, the expression of FGF9 was inversely correlated with miR-187 expression in NSCLC cancer tissues (P < 0.05, r = −0.424)." (PMID 31884893, 2020). "The enhanced expression of FGF9 in a subset of HCC may be caused by deregulated miRNAs, as has been described for cells derived from HCC and other cancer entities." (PMID 32378800, 2020). "FGF9 activation of FGF/FGFR signals has been reported in some kinds of cancers." (PMID 27166269, 2016). "In recent years, activation of FGF/FGFR signals through FGF9 has been reported in some cancers." (PMID 25793394, 2015). "Aberrant expression of FGF9 usually results in human malignancies including cancers, but the mechanism remains largely unknown." (PMID 24334956, 2014). "Nevertheless, the mechanism of how FGF9 protein is elevated in cancer cells remains largely unknown." (PMID 24334956, 2014). "In addition, TPAC cancer cells overexpressed Fgf9, which promotes proliferation of neuronal precursors, Nrg1, which has been shown to drive proliferation and/or induce myelin differentiation, and Nrg4, which is involved in the establishment of early sensory innervation in the skin." (PMID 37607005, 2023). "In addition, we examined whether FGF9 induced the expression of MMPs, which play a pivotal role in invasion of various cancers." (PMID 25925261, 2015). "As translational control provides cells with the plasticity and flexibility to respond to rapid changes in the environment, we hypothesized the increase of FGF9 protein resulted from the response to the microenvironmental change (i.e.hypoxia) in the cancer cells." (PMID 24334956, 2014). "The molecular mechanismsof cancer pathway genes were deactivated,including COX, GJA1, CD44, FGF9, and CCND1." (PMID 38481680, 2024). "An FGF9 mutant (R108E) was defective in integrin binding, activating FRS2α and ERK1/2, inducing DNA synthesis, cancer cell migration, and invasion in vitro." (PMID 38391921, 2024). "Our group has recently shown that in EG cancer models, the overexpression of FGFR3 and Fibroblast Growth Factor 9 (FGF9) sustains acquired resistance to trastuzumab, through the activation of PI3K/AKT/Mammalian target of the rapamycin (mTOR) signaling pathway." (PMID 36983691, 2023). "Fgf9 from tuft cells is predicted to target Fgfr1 on fibroblasts in both PRN and PRT, and epithelial cells through Fgfr1 or Fgfr2 in PRT cancer model." (PMID 37386128, 2023). "It has been found that intracellular FGF9 (fibroblast growth factor 9), a member of the FGF family, is abnormally expressed in various cancers including lung, prostate, ovarian, and endometrioid cancers." (PMID 34575133, 2021).
cancer (continued). "Among 164 genes specific for NASH-fib, we focused on fibroblast growth factor 9 (FGF9), which was the most upregulated gene in the ‘pathways in cancer’." (PMID 31862949, 2019). "FGF9 is a secretory protein of the FGF family, whose expression has been reported in certain types of carcinomas in liver and other organs." (PMID 31862949, 2019). "According to VEGF and FGF-9 elevated EGF expression supports fibrogenesis and the subsequent development of cancer." (PMID 26807786, 2016). "RNA sequencing analysis revealed that activated fibroblasts exhibited distinct gene expression patterns in each etiology, and we focused on fibroblast growth factor 9 (FGF9), which belongs to the ‘pathways in cancer’ selectively upregulated in the activated fibroblasts from MC4R-KO mice." (PMID 31862949, 2019). "In particular, growth-regulated protein (GRO), ENA-78/CXCL5, TIMP-2, and leptin were strongly up-regulated in malignant seroma, whereas IGFBP-1 (insulin-like factor binding protein-1), IL-3, IFN-γ, FGF-9 and IL-16 were down-regulated in malignant versus benign seroma fluid." (PMID 26361584, 2015). "The well-documented cancer-inducing ligands FGF1 and FGF9 are both highly expressed in Cepi." (PMID 23762861, 2013). "Given the potency of FGF9 in this mouse model and the absolute requirement for signaling through FGFR3, this study validates the D11 antibody as a potentially useful and effective reagent for treating human cancers or other pathologies that are dependent on activation of FGFR3." (PMID 27056048, 2016). "However, the function of FGF9 has not been well characterized in most cancers, and FGF9 could well have dual roles, as both a pro-and anti-tumorigenic factor whose function could be context/tissue dependent." (PMID 26361584, 2015).
infection (5 papers, 2019 to 2025). The state of being infected such as from the introduction of a foreign agent such as serum, vaccine, antigenic substance or organism. "Taken altogether, these results demonstrate that forced overexpression of FGF9 in club cells increases susceptibility to different respiratory viruses, but only if overexpression is initiated prior to infection." (PMID 35675358, 2022). "Increased susceptibility to WSN required FGF9 overexpression prior to infection." (PMID 35675358, 2022). "The molecular mechanism underlying how club cell-driven FGF9 overexpression might promote a type I IFN signature upon infection remains unclear." (PMID 35675358, 2022). "We next scored histopathology in tissue sections collected from DOX-treated FGF9-OE and control mice at early (1 dpi) and late (6 dpi) infection time points." (PMID 35675358, 2022). "We also observed pervasive inflammation of the airway epithelium and, most significantly, the lung parenchyma during IAV infection, correlating to when the FGF9-OE mice began to succumb to infection." (PMID 35675358, 2022). "Given the increased alveolar inflammation we observed in FGF9-OE mouse lungs, we next evaluated if these mice displayed elevated cytokine and chemokine expression throughout infection." (PMID 35675358, 2022). "Future work will assess if FGF9 overexpression after IAV infection is cleared from the lungs will promote beneficial post-infection lung repair by increasing the number of BASCs in the regenerating lung." (PMID 35675358, 2022). "FGF9-OE mice were given DOX 1 day prior to infection (d-1) or 1 day post infection (d+1), were infected with WSN at d0, and were monitored for survival." (PMID 35675358, 2022). "FGF9-OE mice succumbed to severe disease, characterized by accelerated infection of alveolar cells and exacerbated inflammation." (PMID 35675358, 2022). "In stark contrast, we identified extremely low levels of infection of the conducting airway epithelial cells in the FGF9-OE mice with approximately 14% of airways infected." (PMID 35675358, 2022). "Alternatively, FGF9 signaling may directly disrupt the barrier function of the conducting airway epithelium, allowing virus to leak into the alveolar space during early infection." (PMID 35675358, 2022). "Future work will assess whether AT2-driven FGF9 overexpression will similarly increase alveolar cell infection or instead protect the alveolar epithelium from infection in a similar manner as seen in the FGF9-OE airway epithelium." (PMID 35675358, 2022). "FGF9-OE mice displayed elevated and persistent viral loads, increased expression of cytokines and chemokines, and increased numbers of infiltrating immune cells as early as 1 day post-infection (dpi)." (PMID 35675358, 2022). "Finally, it is possible that FGF9 secreted from club cells signals directly to alveolar epithelial cells and promotes their infection." (PMID 35675358, 2022). "Gene expression analysis showed an elevated type I interferon (IFN) signature in the conducting airway epithelium and analysis of IAV tropism uncovered a dramatic shift in infection from the conducting airway epithelium to the alveolar epithelium in FGF9-OE lungs." (PMID 35675358, 2022). "However, FGF9-overexpressing mice displayed excessive lung inflammation and alveolar edema, increased cytokine and chemokine expression, accelerated infection in the alveolar space, and increased mortality." (PMID 35675358, 2022). "However, mice that express and secrete FGF9 from club cells in the conducting airway had more severe respiratory virus infection and a hyperactive inflammatory immune response as early as 1 day post-infection." (PMID 35675358, 2022). "Two of these genes, Fibroblast growth factor 9 (fgf9) and Keratinocyte Growth Factor (fgf7) were upregulated in the ear >40-fold 5d post-VACV infection in WT mice." (PMID 38543790, 2024).
infection (continued). "We found that the FGF9-OE airway epithelium had a marked reduction in IAV infection at 1 dpi, but this was accompanied by an increase of infection in the alveoli." (PMID 35675358, 2022). "Instead, high FGF9 signaling sensitizes the airway epithelial cells to induce a rapid, dramatic IFN signature, especially type I IFN, in response to infection in conducting airway epithelial cells." (PMID 35675358, 2022). "Additionally, FGF9 may instead signal on nearby fibroblasts or resident immune cells which in turn promote an elevated IFN response in the airway epithelial cells during infection." (PMID 35675358, 2022). "Although we expected the FGF9-OE mice to be protected from IAV infection, all FGF9-OE mice lost weight and succumbed to infection between 5–9 dpi." (PMID 35675358, 2022). "FGF9-OE mice given DOX on d-1 displayed intermediate lethality compared to what we observed when treatment was initiated on d-3, with approximately 45% of the mice recovering from infection." (PMID 35675358, 2022). "Nevertheless, the infection was also able to repress extracellular exosome-related genes, such as complement C7 (C7) in the R line of the HSF flock, and fibroblast growth factor 9 (FGF9), cadherin 16 (CDH16), and FGG, in the R line of the TSF flock." (PMID 30678719, 2019). "In our FGF9-OE mouse model, FGF9 could be similarly acting on AT2 cells and promoting infection." (PMID 35675358, 2022). "Single-cell suspensions from whole, right lungs of DOX-induced FGF9-OE and control mice were generated after 3 days of DOX but without infection (0 dpi) and at 1 dpi, and the total number of immune cells were quantified by flow cytometry." (PMID 35675358, 2022). "FGF9-OE and control mice were administered DOX beginning at d-3, infected with WSN at day 0, and the right lung lobes were taken from mice after 3 days of DOX but without infection (0 dpi) or at 1, 3, or 5 dpi." (PMID 35675358, 2022).
lip (3 papers, 2019 to 2023). "The fibroblast growth factor 9 (FGF9) T > c mutation has been reported in a non-syndromic bilateral cleft lip and palate case." (PMID 33959039, 2021).
adenocarcinoma (2 papers, 2015 to 2017). A common cancer characterized by the presence of malignant glandular cells. "Furthermore, ectopic activation of Fgf9 in adult lung results in the rapid formation of adenocarcinoma, without associated mesenchymal hyperplasia." (PMID 25978641, 2015).
heart disease (1 paper, 2025). "To date, FGF9 has been extensively studied in heart disease." (PMID 40526701, 2025).
kidney disease (1 paper, 2025). "However, the role of FGF9 in kidney disease has been rarely reported." (PMID 40526701, 2025).
skeletal dysplasia (1 paper, 2015). Any Mendelian diseases that affects growth and development of the skeleton. "This mutation is present in most cases of skeletal dysplasia and is responsible for the overexpression of FGFR3 that, in the presence of its ligand, FGF9, results in toxic effects leading to altered cellular growth." (PMID 26445212, 2015).
FGF9 also shares sentences with these, for which no sentence is quoted: ovarian endometrioid adenocarcinoma (4 papers); fibrosis (3); cervical cancer (2); lymph node metastasis (2); pleuropulmonary blastoma (2); Type 2 Diabetes (2); acute myeloid leukemia (1); aneurysm (1); aortic aneurysm (1); aortic valve stenosis (1); Apert syndrome (1); chondrocalcinosis (1); colorectal adenoma (1); conductive hearing impairment (1); conductive hearing loss (1); connective tissue disorder (1); COVID-19 (1); craniosynostosis syndromes (1); diabetic nephropathy (1); ductal carcinoma in situ (1); heart failure (1); Hyperglycemia (1); hyperopia (1); infectious disease (1); Insulin resistance (1); intestinal cancer (1); keratoconus (1); kidney injury (1); learning disability (1); Leydig cell tumor (1).
A further 19 diseases each share a sentence with FGF9 in 1 paper.